ULK1 (unc-51 like autophagy activating kinase 1)
Diseases named in the same sentence as ULK1 in open-access papers (continued):
Sharing a sentence is not in itself a finding about the gene and the disease.
infection (continued). "Furthermore, we also detected the expression levels of LC3B, NOX2, ULK1, and P70S6K in mouse alveolar macrophages at 6 h after infection." (PMID 38018988, 2024). "LC3 recruitment to vacuoles early during infection is independent of ULK1, requires expression of pore-forming toxin LLO, and can lead to the formation of large vacuoles called SLAPs (spacious Listeria containing phagosomes)." (PMID 36288298, 2022). "In contrast, under pathological conditions (infection or drug treatment), elevated phosphorylated ULK1 (ser 757) protein initiates autophagy, and high mTOR activity does not completely prevent ULK1 (ser 757) phosphorylation to inhibit autophagy in cells." (PMID 36148236, 2022). "Infection with pe6 containing M. smegmatis induced the activatory phosphorylation of MtorC1 (Ser2448) and increased inhibitory phosphorylation of ULK1 (Ser757), whereas no change in the Beclin1 level was observed." (PMID 34322125, 2021). "We next generated ULK1, BECN1, and ATG7 THP-1 cell lines to test whether HIV-1 CA P90A infection could similarly induce the expression of pro-inflammatory genes in cells lacking autophagy." (PMID 33052966, 2020). "Therefore, we determined the colocalization of NOX2 and ULK1 to LC3-positive GAS by immunostaining and confocal microscopy following infection of GAS for 1 h." (PMID 31575768, 2019). "However, mTORC1 activity is restrained by signals including starvation, stress, and pathogen infection, which contribute to the disintegration of the ATG1/ULK1 and mTORC1 complexes, thus initiating autophagy." (PMID 30717138, 2019). "As expected, the down-regulation of ULK-1 and IRGM by siRNA prevented autophagy initiation as shown by the absence of p62 decrease at 6 h post-infection, highlighting an impact of ULK-1 and IRGM on the autophagy process in AIEC-LF82 infected macrophages." (PMID 31694333, 2019). "Immunofluorescence confocal microscopy analysis and quantification show that ~80% of mycobacteria are decorated with Beclin-1 and Atg16L1 but not with ULK1 at 2 h post-infection." (PMID 27242971, 2016). "Knockdown of Rubicon does not affect the cell viability upon Pa infection; however, ULK1 interference resulted in decreased bacterial phagocytosis by macrophages." (PMID 26735693, 2016). "A morpholino knockdown demonstrated that embryo survival, and recruitment of LC3 to vacuoles following infection, required ATG5 but did not require ATG13, a component of the ULK1 complex required to initiate canonical autophagy." (PMID 36288298, 2022). "Whereas infection of control THP-1 macrophages with HIV-1 CA P90A increases the expression of IFNB1, this effect is not seen in ULK1, BECN1, or ATG7 knockout THP-1 cells." (PMID 33052966, 2020). "The requirement of autophagy-initiation proteins ULK1, Beclin 1, and ATG14L and PI3-kinase activity but not elongation proteins ATG5, ATG16L1, ATG4B, ATG7, and LC3B suggested Brucella selectively co-opts autophagy-initiation complexes to subvert host clearance and promote infection." (PMID 38376367, 2024).
neurodegenerative disease (10 papers, 2016 to 2025). A disorder of the central nervous system characterized by gradual and progressive loss of neural tissue and neurologic function. "On the other hand, a marked lowering of STUB1/CHIP levels has already been reported for aberrant autophagic fluxes in neurodegenerative disease, being associated with a parallel downregulation of Ser757 phosphorylated Ulk1." (PMID 39337505, 2024). "Future work should be aimed at exploring the modulation of ULK1 activity for the treatment of neurodegenerative diseases associated with protein aggregates." (PMID 27938392, 2016). "ULK1 thus represents a novel therapeutic target in traumatic and degenerative diseases of the CNS." (PMID 32341448, 2020). "However, it is not fully understood how ULK1 regulates autophagy, especially in the context of protein aggregate prone neurodegenerative diseases." (PMID 27938392, 2016). "In the context of neurodegenerative disease due to impaired autophagy, this suggests that GSK3β may help to promote autophagy not only through the activation of ULK1, but also through preserving levels of transcription factors like TFEB that lead to the upregulation of autophagy-promoting genes." (PMID 37443837, 2023).
Kidney Disease (5 papers, 2019 to 2025). "Consistently, studies in mouse models have demonstrated that reduced function of ULK1, ATG5 or ATG7 in kidney cells is closely associated with various kidney diseases, including DKD59,60." (PMID 41131336, 2025). "Currently, recent studies have yielded many important advances in the understanding of the connection between AMPK/ULK1 signaling pathway and kidney diseases." (PMID 36081940, 2022).
adenocarcinoma (3 papers, 2021 to 2025). A common cancer characterized by the presence of malignant glandular cells. "Spatial analysis supported a strong association between CK19+ adenocarcinoma cells in and pAtg14+ autophagy-active cells in KPC;Ulk1fl/+ tumors, which was largely diminished in Ulk1-deficient mice." (PMID 41408407, 2025). "Further investigation in gastric adenocarcinoma and esophageal adenocarcinoma cell lines revealed that miR-1262 could inhibit cell proliferation, colony formation, cell cycle progression and cell invasion via directly targeting ULK1, an oncogene in adenocarcinoma cells." (PMID 33442421, 2021). "Moreover, ULK1 are capable to accelerate migration and invasion of adenocarcinoma cells." (PMID 33442421, 2021). "To demonstrate the impact of autophagy in lung tumor cell expansion, we first compared gene expression in A549 adenocarcinoma cell lines in which autophagy genes (ATG5 or ULK1) had been deleted or not (GSE73158 dataset)." (PMID 35884522, 2022).
bacterial infection (3 papers, 2018 to 2025). "Macrophage-mediated containment of bacterial infection in our study is dependant on Wnt5A-induced Rac1/Disheveled activation and cytochalasin D inhibitable actin assembly, which is associated with ULK1 kinase activity and LC3BII accumulation." (PMID 29686674, 2018). "Our results underscore the pivotal role of ULK1 in initiating the cellular defense against bacterial infections." (PMID 40853005, 2025).
cardiovascular diseases (3 papers, 2020 to 2023). "Besides, mi-26b, which was confirmed as a protective gene in cardiovascular diseases, was found to connect RXRA with ULK1 in the coregulatory network." (PMID 37596272, 2023).
myopathy (2 papers, 2017 to 2024). A disease of the muscle in which the muscle fibers do not function properly. "Furthermore, the late‐onset myopathy described in muscle‐specific TSC knockout mice was linked to the mTOR‐dependent inhibition of autophagy through ULK1, and the pathology was reminiscent of that in autophagy‐deficient muscle." (PMID 28130275, 2017). "Consistently, the protein expressions of p-AMPK and p-ULK1, the ratio of p-AMPK to AMPK, and the ratio of p-ULK1 to ULK1 were all enhanced in PM muscle with WB myopathy (P < 0.05)." (PMID 38840220, 2024).
CNS tumors (1 paper, 2019). "Collectively, these data demonstrated that pharmacologic inhibition of either ULK1 or VPS34-IN1 successfully inhibits autophagic flux in our BRAFV600E CNS tumor cells." (PMID 31515514, 2019). "As with studies showing synergy between ULK1 and VPS34 inhibitors with mTOR inhibition, our data would support the increased efficacy of autophagy inhibition via ULK1 and VPS34 in CNS tumor cells under stressed conditions." (PMID 31515514, 2019). "Inhibition of ULK1 and VPS34 are potentially viable clinical targets in autophagy-dependent CNS tumors." (PMID 31515514, 2019).
GI tumor (1 paper, 2021). "In GI tumor cells GZ17-6.02 activated an ATM-AMPK signaling module which was responsible for inactivation of mTORC1 and mTORC2, dephosphorylation of ULK1 S757, and increased phosphorylation of ULK1 S317 and of ATG13 S318." (PMID 33898322, 2021).
infectious disease (1 paper, 2025). A disorder directly resulting from the presence and activity of a microbial, viral, or parasitic agent in humans. "Our findings offer new perspectives into the manipulation of ULK1 activity for therapeutic interventions against infectious diseases." (PMID 40853005, 2025).
ULK1 also shares sentences with these, for which no sentence is quoted: cardiac arrhythmia (5 papers); muscular dystrophy (3); amyloid (2); ankylosing spondylitis (2); clear cell renal carcinoma (2); fibrosis (2); Hypercholesterolemia (2); Knee Osteoarthritis (2); Parkinson’s (2); retinal degeneration (2); Werner syndrome (2); Abdominal obesity (1); acute liver failure (1); acute respiratory distress syndrome (1); AL amyloidosis (1); Anxiety (1); Arrhythmia (1); asthenozoospermia (1); Atrophic Gastritis (1); bladder urothelial carcinoma (1); blood pressure (1); brucellosis (1); cervical neoplasms (1); colorectal (1); congestive heart failure (1); Constipation (1); cutaneous melanoma (1); dermatitis (1); developmental delay (1); diabetic retinopathy (1).
A further 51 diseases each share a sentence with ULK1 in 1 paper.